CTLA4 (cytotoxic T-lymphocyte associated protein 4)
Diseases named in the same sentence as CTLA4 in open-access papers (continued):
Sharing a sentence is not in itself a finding about the gene and the disease.
tumor (continued). "Although as a group the IR tumours also had high expression of the negative regulators of immune response PDCD1 (PD-1), CD274 (PD-L1) and CTLA4 (CTLA-4), immunohistochemical expression of these markers was only observed in some cases." (PMID 30153845, 2018). "CTLA4 and PD1 antagonists have been widely used in preclinical and clinical trials due to their ability to enhance tumor-reactive T-cell responses." (PMID 30356111, 2018). "CTLA-4 was consistently expressed at low levels on CD8+ T cells within tumors, with a mean MFI lower than that observed among tumor-infiltrating and circulating Treg cells in mouse models and human tumors." (PMID 29576375, 2018). "IFNγ induces the expression of some tolerant molecules, such as CTLA‐4, PD‐L1 and indolamine‐2,3‐ dioxygenase‐1 (IDO1) on/in tumor cells." (PMID 30039553, 2018). "To check the DNA epigenetic modifications in immune checkpoints/ligand in the breast TME, we examined the promoter CpG methylation profile of genes including PD-1, CTLA-4, TIM-3, LAG-3, PD-L1, and TIGIT in tumor and normal tissues." (PMID 29983831, 2018). "B.longum mediated IL-12 gene delivery significantly inhibited tumor growth and combination therapy with anti-PD1 and anti-CTLA4 synergistically improved these outcomes." (PMID 30400835, 2018). "During CTLA-4 blockade therapy in cancer patients, a marked increase was found in the frequency of T cells expressing inducible co-stimulator (ICOS) in both tumor tissues and blood." (PMID 29857493, 2018). "Shi and colleagues demonstrated that CTLs with knocked-out CTLA4 by CRISPR/Cas9 system significantly repress tumor growth and improve tumor eradication." (PMID 29329591, 2018). "Tumor-infiltrating Tregs are featured in the enhancement of accumulation of forkhead box P3 (Foxp3) together with inhibitory molecules such as PD-1, CTLA-4, LAG-3, and TIM-3 during tumor progression." (PMID 30603054, 2018). "Indeed, a role for Treg cells in modulating tumor-specific effector T lymphocytes by producing immunosuppressive cytokines, such as IL-10 and TGF-β, consuming IL-2 or expressing the inhibitory molecule cytotoxic T-lymphocyte associated antigen (CTLA)-4, has been reported." (PMID 29403496, 2018). "CTLA-4 is structurally similar to CD28 and binds to CD80 (B7-1) / CD86 (B7-2) on APCs (or tumor cells) at a higher affinity than CD28, which suggests an interference with T cell activation." (PMID 29988281, 2018). "All compartments of MSI-H cancers, including tumour-infiltrating lymphocytes (TIL), stroma, and invasive front express many of these molecules, e.g., CTLA4, PD-1, PD-L1, LAG-3, and IDO." (PMID 30173350, 2018). "Major receptors or pathways involved in immunomodulation include vascular endothelial growth factor receptor (VEGFR), epidermal growth factor receptor (EGFR), as well as PD-L1 on tumor cells and the receptors PD1 and CTLA-4 on the site of T cells." (PMID 30577587, 2018). "Analysis of expression of the checkpoint proteins at the RNA level in the LS-CRC tumour indicated low expression of all the markers, including PD1, PD-L1, CTLA-4, TIM3 and LAG3 (FPKM values <1)." (PMID 30108227, 2018). "Immune checkpoint markers, including expression of CTLA-4, TIM3, and Ox40 on CD8+ and CD4+ T cells were examined in the tumor draining lymph node and spleen." (PMID 29844427, 2018). "We found that the distribution of both trimethyl histones in the promoter region of PD-1, CTLA-4, and LAG-3 was reduced in tumor compared with normal tissues." (PMID 29983831, 2018). "Via activation of CTLA4 or PD1, microglial cells can suppress the anti-tumor T-cell response and participate in the generation of an immune suppressive tumor microenvironment." (PMID 30483064, 2018). "A second plausible explanation for resistance to the novel immunotherapies might be the tumor-intrinsic oncogenic signals such as active β-catenin signaling, that mediate T-cell exclusion at the site of the tumor and thus resistance to anti-PD-L1/anti-CTLA-4 therapy." (PMID 29454361, 2018).
tumor (continued). "Tumor growth and survival were studied after administration of ATOR-1015, monotargeting antibodies to CTLA-4, OX40 and/or PD-1." (PMID 30400822, 2018). "As FOXP3 is instrumental for the suppressive function of Tregs, the relative ability of a-CTLA4-TGFβRII and a-CTLA-4 to counteract Treg-mediated suppression of tumor-reactive T cells was also examined using tumor-infiltrated BM from a patient." (PMID 29467463, 2018). "Combining PLX7486 and anti-CTLA-4 or anti-PD-1 in vivo in MC38, B16F10 or MT4 tumor models resulted in increased antitumor effects and a reduction in immune suppression within the tumor microenvironment." (PMID 30400835, 2018). "Thirty‐nine percent of mice treated with anti‐PD‐1, anti‐CTLA4 and an agonist CD40 antibody had long‐term complete tumor remission and prolonged survival." (PMID 30003190, 2018). "PD-1, CTLA-4, TIM-3, LAG-3, TIGIT immune checkpoints and PD-L1, and galactin-9 ligands were selected due to their important role in tumor immune evasion and their potential as therapeutic targets for immune-mediated therapies." (PMID 30081950, 2018). "Pre-clinical and clinical data show CTLA-4 blockade results in the activation of both CD4 and CD8 effector cells in favor of anti-tumor immunity." (PMID 30631766, 2018). "As with the combination of RT and anti-CTLA4, treatment with FTY-720 prior to tumor implantation prevented tumor cure by the combination of RT with anti-PD1 (Logrank survival RT vs RT + anti-PD1 p < 0.05; RT vs RT + anti-PD1 + FTY-720 Not significant)." (PMID 29725089, 2018). "Consistent with a dominant function of human CTLA-4 in CITE, several recent studies including those of our own have demonstrated a critical role for local depletion of Treg cells in the tumor microenvironment." (PMID 29463898, 2018). "The administration of mAbs blocking CTLA-4, PD-1 or PD-L1 allows for the generation of a sustained and specific CTL response capable of tumor cell lysis." (PMID 28866656, 2018). "Thus, the higher CTLA-4 expression not only in Teff and Treg cells, but also in tumor cells, might facilitate tumor cellular lysis through an IPI-dependent cell-mediated cytoxicity by FcRγ expressing immune cells, such as monocytes for Treg or natural killer and lymphocytes Tγδ for tumor cells." (PMID 29682176, 2018). "Because PD-L1 is elevated on tumor cells following BRAF inhibition, and compared to anti-CTLA-4, anti-PD-1 displays lower toxicity, combining BRAFV600E inhibitors with anti-PD-1 therapy seems promising." (PMID 29482595, 2018). "Sunitinib was found to reduce the expression of IL-10, Foxp3, PD-1, CTLA4, and BRAF, but increased Th1 cytokine (IFN-γ) in isolated tumor-infiltrating lymphocytes (TILs) in an MCA26 (colon cancer cells) bearing mouse model." (PMID 29774034, 2018). "A recently developed model using malignancy-specific neoantigens appears to predict tumor response to ICI therapy in patients with melanoma and lung cancer receiving anti-CTLA-4 and anti-PD-1 therapy, respectively." (PMID 29544515, 2018). "Dual targeting of CTLA-4 and OX40, both overexpressed on tumor-infiltrating regulatory T cells (Tregs), directs the effect to the tumor area." (PMID 30400822, 2018). "The phenotypic studies of tumor-infiltrating Treg in relation to CD39 expression were partly based on the immunosuppressive surface molecules analyzed; ICOS, PD-L1 and CTLA-4, which were all increased on CD39+ Treg." (PMID 30651930, 2018). "Blockade of PD1/PD-L1 or CTLA-4 with other therapies has Food and Drug Administration (FDA) approval and is used against several tumor types." (PMID 29377881, 2018). "In particular, tumor-infiltrating CD39+ Treg have high expression of surface molecules related to immunosuppression, such as ICOS, PD-L1 and CTLA-4." (PMID 30651930, 2018).
tumor (continued). "Based on the differential expression between Treg and Teff cells, CTLA-4, GITR, and OX40 appear to be potential targets in all three human tumor subtypes for dual activity antibodies with capacity for ADCC of intra-tumoral Treg cells." (PMID 29576375, 2018). "The outcomes observed with combined PD-1 and CTLA-4 blockade were found to correlate with an increase in CD4+ effector T cell (CD4+ Teff) to Treg cell ratio and CD8+ T cell to Treg cell ratio in tumor tissue." (PMID 29769148, 2018). "IDO expression is also upregulated when cytotoxic T-lymphocyte antigen-4 (CTLA-4) expressed on Tregs binds to CD80 and CD86 on DCs inducing tumor antigen tolerance." (PMID 28447025, 2017). "Significant differences in the CpG-methylation patterns between tumor tissues and matched controls were observed for CTLA4 and PDCD1 (PD1) showing a decreased methylation of these genes compared to matched tumor-free tissues from the same patients." (PMID 28503213, 2017). "Furthermore, co-expression of inhibitory molecules CTLA-4, PD-L1 and PD-L2 on these tumor subtypes indicates the complex biology of tumor cells, suggesting that targeting multiple checkpoints expressed in particular tumors might have an additive therapeutic benefit." (PMID 28148223, 2017). "Hepa1-6 tumor bearing mice after three rounds of treatment with HMGN1, R848 and anti-CTLA4 showed significantly increased infiltration of CD3+, CD4+, and CD8+ T cells in tumor tissues." (PMID 28881713, 2017). "Since CTLA4 is transcriptionally activated by FOXP3, we used this co-stimulatory molecule as a surface signature for the isolation of tumor-CD8+ Treg cells for our study." (PMID 28487507, 2017). "Blood and genomic biomarkers were mainly studied for CTLA-4 ICI, while tumor tissue markers were analyzed for both CTLA-4 and PD-1 ICI." (PMID 29034210, 2017). "Consistent with an increased inflammatory response in tumours, combining intratumoral NDV with systemic CTLA-4 blockade led to regression of both virus-injected and distant tumours." (PMID 28194010, 2017). "Combination studies with other oncolytic virus include NCT02272855 trial, which will analyze CTLA-4 ICKB with HF10, an oncolytic virus that has shown to induce angiogenesis and affluence of CD8+ T-cells at the tumor microenvironment." (PMID 28970830, 2017). "Biomarkers studies of CTLA-4 ICI addressed all biomarker types, whereas PD-1 ICI studies mainly addressed tumor tissue biomarkers." (PMID 29034210, 2017). "Another intriguing example of CpG-mediated anti-tumour effect was reported afterintratumoural injection of the TLR9 agonist CpG, along with anti-OX40Land/or anti-CTLA4 antibodies, to eliminate TREGs in the tumourmicroenvironment." (PMID 28791124, 2017). "Abscopal effects were observed by strategies to improve cross-priming of anti-tumor T cells including stimulation of DC by Flt3-Ligand, treatment with GM-CSF, DC, anti-PD1 and anti-CTLA-4 antibodies." (PMID 28116088, 2017). "Soluble blood factors studied in CTLA-4 ICI-treated patients included S100, circulating tumor DNA, vascular endothelial growth factor, erythrocyte sedimentation rate, C-reactive protein, albumin, and lactate dehydrogenase (LDH)." (PMID 29034210, 2017). "The expression level of CTLA4 only correlated with central tendency parameters, while expression of GLUL, FGFR4, tumour stemness markers KRT19 and EPCAM and immune checkpoint PDCD1 showed significant correlations with MRI heterogeneity parameters only." (PMID 28550313, 2017). "The mechanism of action of anti-PD-1 and anti-CTLA-4 MAbs is to release inhibition on CD4 or CD8 T lymphocytes, which recognize tumor-derived peptides restrictively presented in the context of human leukocyte antigen (HLA) molecules." (PMID 28620382, 2017). "CD4+ T cells in PBMC HC made up a significantly lower proportion of CTLA-4+ T cells (24.8 ± 10.7%) than in PBMC HNSCC (69.3 ± 14.6%; p < 0.0001), whereas percentages in PBMC HNSCC and tumor tissue (61.4 ± 16.3%) were comparably high." (PMID 28574843, 2017).
tumor (continued). "With some exceptions inflammation has been shown to repress adaptive and some innate anti-tumor responses by the direct or indirect release of soluble factors as PGE2, TGF-b, NO or by inhibitory ligands as PD-L1, CTLA4 and TIGIT." (PMID 27664151, 2017). "Expression of CTLA-4 and CXCR2 was the highest and among the highest for CSF1R expression within the TCGA HNSCC cohort compared to other tumor types." (PMID 28915554, 2017). "However, the anti-tumor efficacy of combined lycorine and anti-CTLA-4 therapy remains unknown." (PMID 28416753, 2017). "In the treated tumours, combination therapy of NDV-ICOSL with CTLA-4 blockade resulted in the most marked increase in CD8+ and Tcon cells." (PMID 28194010, 2017). "Despite improved tumour response rates, the combination of anti-PD-1/PDL-1 and anti-CTLA-4 therapies also seems to potentiate grade 3–4 toxicities in cancer patients." (PMID 29237435, 2017). "In comparison to the control group, anti-CTLA-4 treatment significantly increased the percentage of tumor-infiltrating CD8+ T-cells, and decreased tumor-infiltrating Tregs, with a consequent increased ratio of CD8+ T-cells to Tregs." (PMID 28807001, 2017). "In light of the independent impact of S-CTLA-4 in PTs, the delineation of stroma surrounding tumor islets in LN+ needs to be clarified, allowing assessment of CTLA-4 in the tumor microenvironment of N+ disease in future studies." (PMID 28707078, 2017). "The antagonistic RNA aptamer to CTLA-4 was arranged as a tetrameric construct which, due to multivalence-related effects, had enhanced potency in inhibiting CTLA-4 in vitro and tumor immunity in mice." (PMID 28792479, 2017). "Alternatively, a higher mutation rate could increase the number of neo-antigens present on tumor cell surfaces, helping a patient’s innate immune system to identify and eliminate tumor cells that lack immunosuppressive protection such as through the expression of PD-L1 and/or CTLA4." (PMID 28359308, 2017). "A potentially more general role of mutations in tumor rejection has been demonstrated for a larger cohort of cancer patients only after introduction of immune checkpoint modulating antibodies, such as anti-CTLA4 and anti-PD-1, and association of the burden of non-synonymous mutations with response." (PMID 29250075, 2017). "Treatment with combined CTLA4 and PD1 Abs in dKO mice virtually abrogated tumor growth and increased infiltrates of CD8 T cells as well as its effector functions compared with dKO mice treated with control mAbs (p < 0.004)." (PMID 28646041, 2017). "MSI-Hi CRCs were shown to upregulate expression of several immune checkpoints (PD-1, PD-L1, CTLA-4, LAG-3, IDO) in the TILs, stroma, or tumor invasive front compartments, enabling the tumor cells to survive." (PMID 28434400, 2017). "Inhibitory antibodies against immune checkpoint molecules CTLA4 and PD1 induce durable tumor responses in a number of cancer patients, and have become standard of care in a number of metastatic malignancies." (PMID 29123081, 2017). "One study on circulating tumor DNA reported significant correlations to both response and PFS for both CTLA-4 and PD-1 ICI." (PMID 29034210, 2017). "By using high-performance dimensional reduction methodology, we further profile neoantigen-specific, tumour-infiltrating CD8+ T cells and assess the effects of anti-CTLA-4 and anti-PD-1 therapy on these cells and their peripheral counterparts." (PMID 28916749, 2017). "Monoclonal antibodies directed against immune checkpoints including CTLA-4, PD1 or PD-L1 were found to be effective at potentiating radiotherapy, leading to enhanced primary responses and abscopal systemic responses in tumor models in mice." (PMID 28116088, 2017). "Detectable expression levels of CD137 on blood and tumor CD8+ T lymphocytes (and to a lesser extent in CD4+ T cells) at diagnosis were correlated to response to combined anti-PD-1/CTLA-4 mAbs." (PMID 28928380, 2017).
tumor (continued). "In both treated tumours and the spleen, NDV-ICOSL/anti-CTLA-4 treatment resulted in the highest increase in the percentages of CD8+ cells characterized by high expression of Granzyme B and ICOS." (PMID 28194010, 2017). "Given that certain clones of CTLA-4 mAb can deplete CTLA-4 positive Tregs, we measured Treg tumor infiltration following CTLA-4 blockade and found significant but incomplete tumor infiltrating Treg depletion compared to that achieved with CD25 mAb treatment." (PMID 28915554, 2017). "Recent clinical studies targeting co-inhibitory and co-stimulatory immune checkpoints such as cytotoxic T lymphocyte protein-4 (CTLA-4), programmed cell death 1 (PD-1) and its ligand (PD-L1) have demonstrated anti-tumour activity in several cancer types." (PMID 28122336, 2017). "This was in paralleled with the result that maturation of DCs with LPS in the presence of CTLA-4-Fc resulted in robust phosphorylation of STAT3 and incubation of DCs with tumor lysates increased ERK phosphorylation." (PMID 28099147, 2017). "Thus, the therapeutic action of CTLA-4 mAb in tumor may be reduplicated." (PMID 28099147, 2017). "For these experiments, we used the animals with a larger tumour challenge, where tumour control with combination of NDV-WT and CTLA-4 blockade was found to be suboptimal." (PMID 28194010, 2017). "CTLA-4 inhibitors and PD1 blockers act differently by blocking parallel but distinct pathways on tumor cells." (PMID 28848761, 2017). "In an experimental model of glioma, the blockade of three immune checkpoints (IDO, CTLA-4, and PD1) significantly increased the survival of tumor-bearing mice." (PMID 29234674, 2017). "Our data revealed that selumetinib, as a monotherapy, or in combination with anti-CTLA-4, decreased intratumoral CD11b+ Ly6G+ neutrophil or gMDSC cells in the CT26 mouse tumor model." (PMID 28807001, 2017). "Tumor cells can directly escape from T-cell recognition by downregulating MHC class I but upregulating surface ligands, such as PD-L1, CTLA-4, and certain other ligands of inhibitory T-cell receptors, which mediate T-cell exhaustion." (PMID 29115974, 2017). "Other VEGF-triggered immunosuppressive mechanisms are mediated through Treg cells, pro-tumor M2 macrophages, MDSCs, and/or the presentation of immune checkpoint inhibitors, such as PDL1 or CTLA-4 on tumor and effector cells." (PMID 29312351, 2017). "Recent studies show that tumor-infiltrating Tregs can induce much higher expression of many immune checkpoint molecules such as LAG-3, TIM-3, GITR, CTLA-4 and PD-1, making them feasible targets for ICPI." (PMID 29312592, 2017). "The highest frequency of PD-1, CTLA-4 and OX40 triple-positive cells were found in the Treg population isolated from the tumor." (PMID 27195113, 2016). "Similar to CTLA-4, up-regulation of IDO1 or TDO2 allows tumor cells to evade antitumor immunity check from host T cells." (PMID 28027300, 2016). "PD-L1/PD-1 and CD80/CTLA-4 interactions inhibit CD8+ cytotoxic T-lymphocyte proliferation, survival and effector functions of tumour-infiltrating T cells." (PMID 27147225, 2016). "In addition, the tumour-restricted transduction of immune checkpoint inhibitors may be less efficient than their systemic administration in cases where these antibodies target molecules such as CTLA-4, which act primarily in lymphoid organs." (PMID 26751469, 2016). "This raises an interesting question regarding ICI and the role of CTLA-4 on Tregs: how can ICI induce tumor regression and anti-tumor immune responses, if both Tregs and Teff are expanded and activated during treatment?" (PMID 27509527, 2016). "After injection of the tumor-bearing mouse model, the plasmid carrying the CTLA4 and PSCA fusion gene showed stronger inhibition of tumor growth than the plasmid expressing PSCA alone." (PMID 27783810, 2016). "Tumor volume, as analyzed by the IVIS instrument, was significantly smaller after mice CTLA-4 blockade, compared with the control groups (p = 0.001)." (PMID 27105511, 2016).